MTOR (mechanistic target of rapamycin kinase)
Diseases named in the same sentence as MTOR in open-access papers (continued):
Sharing a sentence is not in itself a finding about the gene and the disease.
colorectal cancer (continued). "Our previous research has confimed that HHT inhibited human colorectal cancer cell proliferation and induced the cell apoptosis by blockage of mTOR signaling pathway." (PMID 33867824, 2021). "Further study found that MetS-genes were associated with the effectiveness of targeted chemotherapy for CRC and the MetS core gene IL6 would promote the malignancy of colorectal cancer through mTOR-S6K signaling." (PMID 33582655, 2021). "Ursolic acid can regulate PI3K/AKT/mTOR signal pathway and hinder the development of colorectal cancer." (PMID 33841805, 2021). "AZGP1 has been reported to inhibit colorectal cancer progression via the mTOR signaling pathway and has also been shown to suppress the progression of malignant soft-tissue sarcoma cells." (PMID 33834191, 2021). "Gedatolisib is a dual PI3K and mTOR inhibitor which is under clinical evaluation for multiple types of malignancies, including colorectal cancer." (PMID 33593355, 2021). "Increased glutamine metabolism resulting from CDK4/6 inhibition in breast and colorectal cancer cells has been shown to be dependent on MYC-driven activation of mTOR." (PMID 33572972, 2021). "ATL-1 was found to inhibit melanoma and colorectal cancer cell proliferation via the JAK2/STAT3 or AKT/mTOR signaling pathway." (PMID 34692516, 2021). "CXCL12 derived from stromal cells in the tumor microenvironment depends on PI3K/Akt/mTOR signal to up-regulate the secretion of CXCL6 or down-regulate the expression of PTEN through PI3k/Akt signal to enhance the liver metastasis of colorectal cancer." (PMID 34930323, 2021). "TIMD4 promoted the growth of colorectal cancer by activating angiogenesis and recruiting tumor-associated macrophages through the PI3K/AKT/mTOR signaling pathway." (PMID 34476011, 2021). "The majority of mutations found in colorectal cancer (CRC), including alterations in the WNT pathway as well as activation of RAS/MAPK and PI3K/AKT and, subsequently, mTOR signaling, lead to deregulation of the translational machinery." (PMID 32455578, 2020). "On the mTOR signaling pathway, nobiletin also protects cadmium-induced neurotoxicity induced by cadmium and increases the sensitivity of colorectal cancer to oxiplatin." (PMID 32212785, 2020). "As a key oncogenic signaling pathway, PI3K/AKT/mTOR pathway plays a pivotal role in various cancers, including colorectal cancer." (PMID 32209115, 2020). "The PI3K/Akt/mTOR signaling pathway was over-activated in liver cancer, colorectal cancer, and esophageal cancer lesions." (PMID 33134320, 2020). "The downregulation of long noncoding RNA RP11-708H21.4 is associated with a poor prognosis in colorectal cancer and promotes tumorigenesis by regulating the AKT/mTOR pathway." (PMID 32117463, 2020). "More importantly, it was previously demonstrated that deoxyshikonin exhibited anti-proliferative and pro-apoptotic activities in colorectal cancer cells through the phosphoinositide 3-kinase (PI3K)/Akt/mTOR pathway." (PMID 32850379, 2020). "CAFs upregulated UCA1 expression in colorectal cancer cells, possibly through mTOR-related pathways, which was crucial for the pre-metastatic niche." (PMID 33050642, 2020). "In summary, we provided experimental evidence suggesting for the first time a novel role for miR-3135b in the protection of chemotherapy-induced Golgi fragmentation via GOLPH3/AKT1/mTOR axis and protective autophagy in colorectal cancer cells." (PMID 32601379, 2020). "In fact, the gene expression of the PI3K/Akt/mTOR signaling axis in human colorectal cancer are significantly overexpressed compared to normal colonic tissues." (PMID 32709256, 2020). "Consistent with this, pharmacologic and genetic inhibition of mTOR decreases colorectal cancer cell migration and invasion." (PMID 33293473, 2020).
colorectal cancer (continued). "There is a recent preclinical study with OSI-027, a potent inhibitor of Akt/mTOR which suppressed the growth of colorectal cancer." (PMID 32566099, 2020). "Tim-4 was upregulated in colorectal cancer and promoted the growth of colorectal cancer by activating angiogenesis and recruiting tumor-associated macrophages via the PI3K/AKT/mTOR signaling pathways." (PMID 32300343, 2020). "The epidermal growth factor receptor (EGFR), through the MAP kinase and PI3K-Akt-mTOR axis, plays a pivotal role in colorectal cancer (CRC) pathogenesis." (PMID 33233823, 2020). "The anti-angiogenic effect of cinobufagin by suppressing the mammalian target of rapamycin (mTOR) and hypoxia-inducible factor-1α (HIF1α) signaling pathways has also been observed in colorectal cancer." (PMID 32933177, 2020). "Particularly, downregulation of EZH2 was found as an epigenetic modulator of autophagy by regulating the mTOR pathway in the colorectal carcinoma." (PMID 33304896, 2020). "Increased mTOR activation leads to tumor growth, while mTOR inactivation reduces tumor growth in colorectal carcinoma." (PMID 31906582, 2020). "Metastasis and tumor growth in colorectal carcinoma is often promoted by a signaling pathway in which the mammalian target of rapamycin (mTOR) plays a crucial role." (PMID 31906582, 2020). "At the same time, adiponectin also induces AMPK and inhibits mammalian target of rapamycin (mTOR) cascade in colorectal cancer cell lines." (PMID 31121868, 2019). "The OGT‐DDX5 axis affects colorectal cancer progression mainly by regulating activation of the AKT/mTOR signalling pathway." (PMID 30484950, 2019). "Our previous study demonstrated that administration of NVP-BEZ235 (BEZ235), a dual PI3K/mTOR inhibitor, before radiotherapy (RT) enhanced the radiotherapeutic effect in colorectal cancer (CRC) cells both in vitro and in vivo." (PMID 31430901, 2019). "miR-99b is reported to be dysregulated in many pathophysiological conditions and miR-99b mediated mTOR regulation is also investigated in pancreatic cancer, colorectal cancer etc46,47." (PMID 30718795, 2019). "Proliferation and survival related signaling pathways such as PI3K/AKT/mTOR and RAS/RAF/MEK/ERK play important roles in pathogeneses of solid tumors, and KRAS, BRAF, and PIK3CA (PI3K) mutations are the most common in colorectal cancer." (PMID 31624493, 2019). "mTOR signaling is accepted as one of the primary mechanisms for sustaining tumor outgrowth and metastasis and is dysregulated in many cancers, including colorectal cancer." (PMID 31608109, 2019). "In this study, we demonstrated that O‐GlcNAcylation of DDX5 is involved in colorectal cancer progression by activation of AKT/mTOR signalling pathway, which opens up a new sight for the treatment of colorectal cancer." (PMID 30484950, 2019). "It was revealed that hesperidin supplementation initiated apoptosis via targeted inhibition of constitutively activated Aurora-A-mediated PI3K/Akt/GSK-3β and mTOR pathways in colorectal cancer." (PMID 31269749, 2019). "The synergistic anti-neoplastic efficacy of combined MEK and mTOR inhibitors has been demonstrated in melanoma, lung, and colorectal cancer, where it resulted in profound tumor cell apoptosis and inhibition of tumor cell proliferation." (PMID 31277283, 2019). "Duan and colleagues found that the PI3K/ATK/mTOR pathway was related to invasion, migration, and proliferation of colorectal cancer induced by IMPDH2." (PMID 30870998, 2019). "We overexpressed DDX5 or added an mTOR agonist (MHY1485) in the OGT knockdown colorectal cancer cell line." (PMID 30484950, 2019). "In the previous study, we found that compound-7g was an effective inhibitor against colorectal cancer cells through impairing PI3K/AKT/mTOR signaling pathway." (PMID 31357480, 2019). "Taken together, these results indicated that OGT‐mediated O‐GlcNAcylation stabilizes DDX5, promoting activation of the AKT/mTOR signalling pathway, thus accelerating colorectal cancer progression." (PMID 30484950, 2019).
colorectal cancer (continued). "Sal-B induced cell death and triggered autophagy in HCT116 and HT29 colorectal cancer cells via suppression of AKT/mTOR pathway." (PMID 31726654, 2019). "Representative pathways that were downregulated in the majority of subjects included other important pathways related to colorectal cancer, such as valine, leucine, and isoleucine degradation, mTOR signaling pathway, and cell cycle." (PMID 31608109, 2019). "Accordingly, upregulation of the PI3K/mTOR pathway, often through loss of PTEN function, occurs in diverse cancers, including gastrointestinal adenocarcinoma, colorectal cancer, and esophageal squamous cell carcinoma." (PMID 30863440, 2019). "SNHG7, whose high expression was correlated with poor prognosis, acted as a target of miR-34a to increase GALNT7 level and regulate PI3K/Akt/mTOR pathway in colorectal cancer progression." (PMID 31164492, 2019). "CM downregulated the levels of phosphorylated AMPK, what indicates that MSCs promote the progression of colorectal cancer through AMPK/mTOR-mediated NF-κB activation." (PMID 30310111, 2018). "In a previous report, we showed that gankyrin significantly enhanced the mTOR activity in colorectal cancer (CRC) through targeting TSC2 for degradation, independent of AKT signaling." (PMID 30420909, 2018). "Amino-acid metabolism plays a vital role in mammalian target of rapamycin (mTOR) signaling, which is the pivot in colorectal cancer (CRC)." (PMID 29867114, 2018). "This suggests that mTOR should be considered as a potential therapeutic target in BRAFV600E-driven colorectal cancer." (PMID 29907857, 2018). "ENO1 has been previously found to promote tumorigenesis and metastasis via the AMPK/mTOR pathway in colorectal cancer." (PMID 29522283, 2018). "More specifically, increased expression of RICTOR is associated with tumor progression and poor survival in CRC, and mTOR activity and complex distribution are independent prognostic factors in colorectal carcinoma." (PMID 29455662, 2018). "Early passaged colorectal cancer liver metastasis cell lines and patient derived xenografts of colorectal cancer liver metastasis were then treated with oxaliplatin and a mTOR inhibitor." (PMID 28060954, 2017). "To our knowledge, we are the first to report inhibition of mTOR pathway through targeting of total mTOR protein to proteasome degradation in colorectal cancer cells." (PMID 28912474, 2017). "Specifically, the combination of oxaliplatin and a mTOR inhibitor (everolimus) can potentially be used in the treatment of colorectal cancer liver metastasis." (PMID 28060954, 2017). "Treatment of early passaged colorectal cancer lines and patient derived xenografts with oxaliplatin resulted in activation of the mTOR pathway." (PMID 28060954, 2017). "Our results suggest that the combination of oxaliplatin and mTOR inhibition can be used effectively to treat patients with colorectal cancer liver metastasis." (PMID 28060954, 2017). "Akt activation by insulin produced markedly lower levels of LC3-II conversion in the TCO-treated cells than in the controls, suggesting that TCO induced autophagy in colorectal cancer cells by inhibition of the Akt/mTOR pathway." (PMID 28881770, 2017). "Recently, aspirin was also reported to exert a protective effects against development of colon cancer cells through inhibition of mTOR and induction of autophagy in colorectal cancer cells." (PMID 28912474, 2017). "BKM120, a direct PIK3CA inhibitor, and BEZ234, a dual PIK3CA and mTOR inhibitor, exert pro-apoptotic effects on gastric and colorectal cancer cell lines." (PMID 29207615, 2017).
colorectal cancer (continued). "One potential agent to target mTOR in colorectal cancer is everolimus (RAD001) and there have been several early studies of the mTOR inhibitors suggesting some benefit in these patients." (PMID 28060954, 2017). "MiR-99b acts in promoting metastasis and in defining poor prognosis in HCC patients or, on the other hand, in suppressing liver metastasis of colorectal cancer by mTOR downregulation." (PMID 28881825, 2017). "Our data suggest potential usefulness of InsP6 as a novel therapeutic modulator of AKT/mTOR signaling cascade, an important prognostic factor in human colorectal cancer." (PMID 28972559, 2017). "DBT induced autophagic death of colorectal cancer cells through the upregulation of Atg7 and modulation of the mTOR/p70s6k signaling pathway." (PMID 29179457, 2017). "Taken together, our results demonstrate, for the first time, that Sal B is a novel autophagy inducer and exerts its antitumor activity as a single agent in colorectal cancer cells through the suppression of AKT/mTOR pathway." (PMID 27557491, 2016). "For example, by downregulating mTOR signaling and energy metabolism, it is possible to suppress the malignant phenotype of colorectal cancer cells." (PMID 27213347, 2016). "Our data highlight the importance of the PDGF-PI3K/Akt/mTOR pathway-axis and its potential as a possible weak point in colorectal cancer." (PMID 27626684, 2016). "mTOR signaling pathway is activated in colorectal cancer stem cells, and correlated with the prognosis of colorectal cancer patients." (PMID 27050147, 2016). "This study indicates that MSCs promote the progression of colorectal cancer via AMPK/mTOR-mediated NF-κB activation." (PMID 26892992, 2016). "In colorectal cancer cells and in murine mammary epithelial NMuMG cells, the inhibition of mTOR signaling reduces migration and invasion." (PMID 25699271, 2015). "Immunohistochemical staining for mTOR, EGFR and PTEN was motivated by these markers being key targets that have also been shown to be up-regulated in Lynch syndrome-associated colorectal cancer." (PMID 24848881, 2014). "The median TTF of FBXW7-positive colorectal cancer patients was 3.3 months (1.4–4.4) on mTOR inhibitors versus 1.8 months (0.6–4.9) for FBXW7-negative patients with colorectal cancer (p = 0.27)." (PMID 24586741, 2014). "The authors of that work did in fact provide data indicating that siRNA mediated inhibition of β-catenin expression in the SW480 and DLD-1 colorectal cancer cell lines decreased both total and phosphorylated mTOR levels." (PMID 24763434, 2014). "A total of 4 patients with colorectal cancer and a FBXW7 mutation were treated with an mTOR inhibitor and 3 patients (75%) had SD as their best response." (PMID 24586741, 2014). "The antitumor activities of PI3K/mTOR inhibitors, including PF-04691502, in colorectal cancer remain to be explored." (PMID 23826249, 2013). "We propose that combining TRAIL with PI3 Kinase/mTOR or HSP90 inhibitors has therapeutic potential in the treatment of TRAIL-resistant colorectal cancers." (PMID 23852390, 2013). "Our results not only confirm that PIK3CA mutant tumors are sensitive to treatment with PI3K/mTOR inhibitors but also further elucidate the ability of PI3K/mTOR inhibitors to target mutant CSCs in colorectal cancer." (PMID 23826249, 2013). "Overall, our results suggest that the PI3K/mTOR pathway inhibitor PF-04691502 has potent anti-proliferative activity in PIK3CA mutant CSCs, warranting further evaluation of the inhibitors in colorectal cancer patients carrying PIK3CA mutations." (PMID 23826249, 2013). "Colorectal cancer cells were treated with TRAIL alone or in combination with the representative PI3 Kinase/mTOR inhibitor, PI-103 or the representative HSP90 inhibitor, 17-AAG." (PMID 23852390, 2013). "As such, we sought to determine the ability of the mTOR inhibitor everolimus to potentiate the antitumor effects of irinotecan in colorectal cancer (CRC)." (PMID 23520486, 2013).
colorectal cancer (continued). "Our results indicate the therapeutic potential of combinatorial therapy with PI3 Kinase/mTOR or HSP90 inhibitors in colorectal cancer and suggest useful mechanism-based pharmacodynamic biomarkers." (PMID 23852390, 2013). "Here, our aims were to explore the ability of representative, specific PI3 Kinase/mTOR or HSP90 inhibitors to reverse resistance to TRAIL-induced apoptosis in human colorectal cancer." (PMID 23852390, 2013). "Supporting this, both mTOR complexes mTORC1 and mTORC2 have been reported to regulate motility and metastasis of colorectal cancer via the Rac1 signaling pathway, and Rac1 has been shown to simultaneously regulate mTORC1 and mTORC2." (PMID 23285024, 2012). "Particularly in colorectal cancer, mTOR signaling components were highly activated in tumor specimen compared to non cancerous mucosa." (PMID 20226010, 2010). "Studies on coumarin and p-coumaric acid-loaded fibrin hydrogels have shown their ability to induce apoptosis and autophagy in colorectal cancer cells via the PI3K/Akt/mTOR and AMPK/mTOR pathways, highlighting their role in tumor suppression and potential applications in oncological treatments." (PMID 40277696, 2025). "The m6A “writers” METTL3 and m6A “readers” IGF2BP2/3 were found to participate in the methylation of VEGFA to prevent mRNA degradation, and to promote angiogenesis in colorectal cancer by mimicking the formation of the PI3K/AKT/mTOR and ERK1/2 signaling pathways." (PMID 40316995, 2025). "Specifically, TIGAR contributes to ferroptosis resistance in colorectal cancer via the ROS/AMPK/SCD1 axis, while aspirin enhances RSL3-driven ferroptosis by inhibiting mTOR/SREBP-1 (sterol regulatory element-binding protein-1)/SCD1-regulated lipogenesis in PIK3CA-mutant colorectal cancer." (PMID 39935430, 2025). "DLX6-AS1 was found to regulate PIK3CA and MTOR in colorectal cancer." (PMID 40149330, 2025). "Although accumulating evidence has linked mTOR signaling to tumor immunometabolism, how TSC1 modulates glycosylation-dependent immune evasion in colorectal cancer remains largely unknown." (PMID 41445741, 2025). "Additionally, RES has been shown to modulate the mTOR signaling pathway, inhibiting glycolysis and proliferation in colorectal cancer cells." (PMID 40697554, 2025). "Notably, both insulin resistance and glycerophospholipid metabolism have been linked to colorectal cancer (CRC) progression, potentially facilitating tumor growth and survival through the PI3K-AKT and mTOR signaling pathways." (PMID 41293172, 2025). "Similarly, combined AKT and mTOR inhibition yielded synergistic anti-proliferative effects in colorectal cancer cell lines and patient-derived spheroids." (PMID 40729043, 2025). "Therefore, we decided to investigate further if mTOR signaling in our colorectal cancer patient cohort in connection with CAVIN1 levels." (PMID 40269326, 2025). "Meanwhile, RPTOR, a crucial component of the mTOR pathway, regulates cell growth in response to nutrient and insulin levels and has been reported as a key driver gene in the brain metastasis of lung and colorectal cancer progression." (PMID 41226303, 2025). "Thus, we proposed that phillyrin hinders PI3K/AKT/mTOR signaling pathway activation, decreases mTOR downstream effector activation, and ultimately inhibits colorectal cancer proliferation and EMT progression." (PMID 41142018, 2025). "Our in vitro experiments revealed a novel mechanistic insight: MAGEA3 specifically inhibits the expression and secretion of VEGF through the mTOR signaling pathway in colorectal cancer cells, while exhibiting minimal impact on other key angiogenic factors such as PDGF, FGF, and ANGPT2." (PMID 40342736, 2025). "As a result, the use of MEK inhibitors in conjunction with PI3K, AKT, or mammalian target of rapamycin (mTOR) inhibitors has not led to desirable outcomes in the treatment of KRAS-mutated colorectal cancer in clinical settings." (PMID 40519270, 2025).